ALK (ALK receptor tyrosine kinase)
Diseases named in the same sentence as ALK in open-access papers (continued):
Sharing a sentence is not in itself a finding about the gene and the disease.
tumor (continued). "In this study, conteltinib (CT-707) showed manageable safety profile, favorable PK properties, and anti-tumor activity in advanced ALK-positive NSCLC patients." (PMID 36424628, 2022). "When the inhibition of ALK fusion proteins is alleviated, these changes allow tumor cells to survive and proliferate, leading to the development of ALK TKI resistance." (PMID 35211406, 2022). "To mention, the second generation ALK inhibitor ceritinib showed a synergistic effect with PD-1/PD-L1 blockade to provide an improved anti-tumor response along with favorable side effect tolerability in vivo NSCLC xenograft model and clinical trial." (PMID 35646685, 2022). "In particular, ALK tumor expression has been reported in MCC and was recently shown to correlate with viral status as well as a longer survival." (PMID 35551625, 2022). "Other than identification of ALK rearrangements from tissue biopsy, non-invasive genotyping of circulating tumor nucleic acids has gained attention as an alternative strategy." (PMID 35463328, 2022). "Although first discovered as a rearranged gene in anaplastic lymphoma, ALK gene fusions have been documented in numerous tumor types." (PMID 36337169, 2022). "Recently occurred keywords included “SCLC”, “irAEs”, “anaplastic lymphoma kinase (ALK)”, “biomarker”, “atezolizumab”, “duvalumab”, “radiomics”, “tumor mutation burden (TMB)”, “tumor burden”, “chemoradiotherapy”, and “microbiome”." (PMID 36532038, 2022). "We next investigated the effect of FGFR and ALK pathway inhibition on tumor–stroma crosstalk and angiogenesis." (PMID 35326668, 2022). "Generation of the NPM-ALK translocation enabled reproduction of the heterogeneous ALK+ ALCL tumor phenotype." (PMID 35246138, 2022). "Subsequently, we demonstrated that inhibiting TOPK enhanced tumor sensitivity to alectinib (an ALK inhibitor)." (PMID 36167821, 2022). "For further investigation, ALK+ tumor models with differential TLS formations would help explore the direct roles of TLS and the underlying mechanisms." (PMID 36233802, 2022). "ALK+ ALCL tumor cells also develop ALK TKI resistance through amplification of NPM–ALK, which was shown to be overexpressed in ALK+ALCL-resistant cell lines." (PMID 35211406, 2022). "Overexpressed ALK fusion protein increased PD-L1 level, promoting the apoptosis of tumor-infiltrating T cells." (PMID 35062949, 2022). "The addition of ALK-TKIs to radiotherapy can increase radiosensitivity of tumor cells strengthening the rational for combined strategies." (PMID 35158987, 2022). "The Immunohistochemistry of this tumor was strongly positive for ALK, which proved a local recurrence of IMT in the uterine cavity." (PMID 36550868, 2022). "Gefitinib, crizotinib and afatinib are kinase inhibitors that are used to treat tumours that exhibit EGFR mutations, ALK fusions and ERBB2/HER2-amplification, respectively." (PMID 35781872, 2022). "The current study found that ALK can promote tumor cell proliferation and survival by activating signaling pathways including PI3K, JAK/STAT, and MAPK." (PMID 36591504, 2022). "Tumor cells isolated from the various organs were primarily CD3- but expressed ALK (high expression levels; both nuclear and cytoplasmic), CD30 and PDL1." (PMID 35246138, 2022). "Confirmatory IHC showed expression of both ALK and mutation-specific EGFR-L858R protein in the same tumor cells, despite the generally mutually exclusive occurrences of driver mutations in treatment-naïve lung cancers." (PMID 36153311, 2022). "The AcSé program in France supported a multi-tumor phase II trial wherein 107 pediatric tumors were analyzed for alterations in the molecular targets of crizotinib (ALK, MET, and ROS-1)." (PMID 36034555, 2022). "The significance of TLS and ETLS-IC features on tumor size, node metastasis, and pStage of ALK+ LUAD was examined by logistic regressions." (PMID 36233802, 2022).
tumor (continued). "It is likely that the signal pathway of downstream ALK is blocked after patients received targeted therapy with immune checkpoint inhibitors, leading to the suppression of growth and invasion of tumor cells and better therapeutic effect." (PMID 36401689, 2022). "Activation of the MEK pathway also contributes to ALK TKI resistance, mainly through deficiency/low expression of Wiskott–Aldrich syndrome protein (WASP), a tumor suppressor whose loss leads to tumor development and invasion." (PMID 35211406, 2022). "Nonetheless, the circumvention of EMT-associated resistance to ALK–TKIs to restore the sensitivity of mesenchymal-type tumor cells to ALK–TKIs, remains an unmet need of targeted drug therapy in ALK-rearranged NSCLC." (PMID 36551587, 2022). "Tumour cells with oncogenic activating mutations in the EGFR (epidermal growth factor receptor), ALK (anaplastic lymphoma kinase) or RET (rearranged during transfection) kinases were found to reduce MHC-I expression." (PMID 35343573, 2022). "This was followed by differential methylation analysis (cases vs. controls) and biomarker validation using 5-mC profiles of ALK-positive tumor tissues." (PMID 36461127, 2022). "Using targeted proteomics tools within a set of various cancer models we describe here the discovery and characterization of a composite phosphorylation signature associated with tumor addiction to four distinct oncogenes, MET, EGFR, ALK and BRAF." (PMID 36494469, 2022). "Here, we review the results of recent studies on the immunological relevance of ALK-altered tumors, which provides important insights into the development of tumor immunotherapies targeting this large class of tumors." (PMID 35958559, 2022). "In NSCLC harboring ALK gene rearrangements are observed ALK fusion proteins with potent transforming activity as oncogenic drivers of tumor growth." (PMID 35408658, 2022). "A few reports tried to decipher the poor responsiveness to PD-1/PD-L1 inhibitors in the ALK+ subgroup from the perspective of tumor immune microenvironment (TIME)." (PMID 36233802, 2022). "The combination of HDACs with ALK inhibitors is an alternative for patients whose tumor develops resistance." (PMID 36263432, 2022). "Tumours harbouring mutations in genes such as EGFR and ERBB2, or gene rearrangements involving ALK, RET, or ROS1 are typically dependent on the oncogene for survival, with profound anti-tumour effects observed in response to the appropriate targeted therapy." (PMID 35326531, 2022). "The concordance of hyper-DMRs found in both ALK cfDNA and cancer tissue confirmed their tumor specificity, which was further validated by the correlation of the 5-mC score to cancer-specific genomic alterations." (PMID 36461127, 2022). "Due to the difficulty of tissue sample collection, circulating tumor cells and cell-free DNA in plasma samples were also investigated to monitor the duration and magnitude of clinical response of patients receiving ALK-TKIs." (PMID 35642002, 2022). "The targeted therapies are tailored to the patient based on the specific genetic background of the tumor (e.g., mutation or altered expression of EGFR, KRAS, BRAF, PIK3CA, PTEN, HER2, or gene fusion of ALK, ROS1, RET)." (PMID 35205667, 2022). "Another key advantage of the presented study was the availability of various in-house reference datasets for marker validation (i.e., cfMeDIP-seq data of ALK tumor tissue and cell-free genomic alterations determined in matched plasma)." (PMID 36461127, 2022). "Recently, studies have found that the expression of PD-L1 and the number of tumor-infiltrating T cells are related to the prognosis of ALK+ ALCL." (PMID 35211406, 2022). "Because CD147 is differentially expressed in ALK+ ALCL versus ALK− ALCL and normal T cells, this gene emerged as a strong candidate for the pathogenesis of this tumor." (PMID 35676454, 2022).
tumor (continued). "In mouse models of ALK+ NSCLC, this ALK DNA vaccine induced strong systemic and intratumoral immune responses, significantly reducing tumor growth and extending the survival of treated mice." (PMID 35958559, 2022). "Tumor cells were positive for staining with the ALK antibody, as seen during immunohistochemical analysis (ALK iScore 5 by iAEP immunohistochemistry)." (PMID 35366157, 2022). "Various preclinical and clinical efforts are underway to identify mechanisms related to the interaction of the ALK gene with the tumor immune microenvironment." (PMID 35958559, 2022). "The tumour microenvironment (TME) in ALK rearranged cancers refers to the interplay of CD4 + T cells, CD8 + T cells, tumour associated macrophages (TAMs), mast cells and regulatory T cells (FOXP3 +)." (PMID 36591504, 2022). "Then, an ALK positive cell line, H3122 (EML4-ALK variant 1), or a patient-derived tumor from EML4-ALK-rearranged (EML4-ALK variant 1) NSCLC patient was transplanted in NSG mice." (PMID 36185084, 2022). "Among 100 tumor-normal pairs sequenced, somatic mutations of 1p tumor suppressors KIF1Bβ and CHD5 were most frequent (2%) after ALK and ATRX (8%), and BARD1 (3%)." (PMID 35768791, 2022). "We next transfected purified CD4+ lymphocytes, which represent the most typical tumor phenotype in ALK+ ALCL, and were able to express active NPM-ALK protein as early as 6 days post-transfection." (PMID 35246138, 2022). "Mouse models of PDAC treated with lorlatinib (an FDA-approved inhibitor of anaplastic lymphoma kinase, or ALK) demonstrated a reduction in tumor progression mediated by inhibition of neutrophil development and mobilization." (PMID 36077772, 2022). "There were a trend or significant differences in PD‐L1 expression between different histological types in NSCLC, different EGFR and ALK status, and different tumor tissue storage time." (PMID 34841687, 2022). "This was followed by differential methylation analysis between cases and controls and biomarker validation in ALK-positive tumor tissues." (PMID 36461127, 2022). "By capturing the vast reservoir of information available by preexisting data of tumor gene expression, we unveiled ALK as a new putative driver gene, assessing the impact of its inhibition on CMS outcomes." (PMID 35351152, 2022). "Off-target mechanisms were shown to be responsible for resistance to ALK-i in up to 55% of both tumor and blood samples, in a large cohort of ALK-rearranged NSCLC patients." (PMID 36230686, 2022). "A dynamic sequencing of circulating tumor DNA (ctDNA) in ensartinib-resistant ALK+ NSCLC patients revealed that ALK-dependent resistance mechanisms of ensartinib were mainly due to G1269A, G1202R, and E1210K mutations." (PMID 35463328, 2022). "In the open-label, phase 1/2 study (NCT01970865), LOR was found to have intracranial and extracranial responses in patients with advanced NSCLC harboring ALK rearrangement, who experienced tumor progression during prior ALK TKI therapy, including alectinib." (PMID 35498380, 2022). "Certainly, future studies utilizing CIK/ALK/PD inhibitors axis in context with the tumor microenvironment of NSCLCs will be of interest." (PMID 35646685, 2022). "In ALK+ patients, CD8+ T cell tumor infiltration decreases and regulatory T cells increase after ALK inhibitor treatment, which induces a lower response rate to ICIs." (PMID 35958559, 2022). "Treatment with alectinib, an ALK inhibitor, led to a significant reduction in tumor size and calcification in the lymph nodes." (PMID 35256912, 2022). "Conteltinib (CT-707) is a potent second-generation anaplastic lymphoma kinase (ALK) tyrosine kinase inhibitor (TKI) showing promising anti-tumor activities in preclinical studies." (PMID 36424628, 2022).
tumor (continued). "Here, we present a first-in-human, phase 1 study in 64 patients and demonstrate that conteltinib (CT-707) has a manageable safety profile as well as favorable PK properties and anti-tumor activity, in patients with ALK-positive NSCLC." (PMID 36424628, 2022). "Mutations in oncogenic factors including EGFR, ALK, BRAF, or MET, which can change the immunological tumor micro-environment, can enhance tolerance to PD1/PD-L1." (PMID 36499382, 2022). "Larger tumor size and presence of EGFR/ALK mutation were predictive of higher rates of starting/changing systemic therapy on multivariate analysis." (PMID 35323340, 2022). "Nevertheless, in NSCLC tumors carrying wild-type EGFR and ALK genes, the brain-seeding metastatic cells acquire additional genetic alterations during the early stages of tumor evolution." (PMID 36561283, 2022). "Through single circulating tumor cell (CTC) sequencing, researchers found that patients with ALK mutation developed acquired drug resistance after ALK-TKIs therapy." (PMID 35912223, 2022). "Thirdly, clinical trials will be carried out to verify the anti-tumor effect of anlotinib monotherapy and combination therapy on ALK-positive patients in the future." (PMID 35642002, 2022). "A comprehensive molecular analysis of the entire population of resected lung tumours is necessary—new generation platforms based on the multigene analyses of DNA and RNA should be exploited to highlight the presence of ALK fusions in early-stage tumours." (PMID 35454856, 2022). "Immunohistochemically, in all ALK+ ALCLs, the tumor cells are positive for CD30 on the cell membrane and the Golgi region and express ALK." (PMID 36010351, 2022). "Specifically, serum miR-1 is upregulated in tumor-bearing mice treated with the ALK inhibitor, while the same miR is unaffected in the serum of mice treated with the FGFR inhibitor." (PMID 35326668, 2022). "Another important reason for tumor progression is ALK fusion gene amplification, which results in the failure of crizotinib to completely inhibit downstream signaling." (PMID 36508072, 2022). "ALK expression in tumor cells was evaluated in 155 cases and detected in 135 (87%), among which 44% were scored as high, 31% as moderate and 24% as low." (PMID 35551625, 2022). "It was observed that patients with tumours harbouring ALK-rearrangements, EGFR and BRAF-mutations had indoor radon levels above the WHO recommendation of 100 Bq/m3, particularly for ALK-rearrangement." (PMID 36208308, 2022). "Altogether, these results demonstrate that PDGFRβ expression facilitates ALK+ tumor formation and dissemination, and that our generated genetic mouse model is a valid tool to study the effects of PDGFRβ in ALK+ ALCL pathogenesis." (PMID 36045346, 2022). "Tumor cells exhibited a uniform strong cytoplasmic immunoreactivity for ALK, expressed AR and NKX3.1 but were negative for the neuroendocrine marker synaptophysin." (PMID 36337169, 2022). "EGFR or ALK status data were available for 82 patients (86.3%), and PD-L1 tumor expression data were available for 76 patients (80.0%)." (PMID 35130287, 2022). "Preclinical findings in ALCL suggest that the degree of PD-L1 expression on the surface of tumour cells is positively correlated with TAMs in ALK positive ALCL." (PMID 36591504, 2022). "Tumor samples from patients with ALK-rearranged (N = 39) and EGFR- (N = 40)/KRAS- (N = 30) mutated NSCLC were collected." (PMID 36159860, 2022). "At this time, it is not known if one of these newer agents would yield improved efficacy in these other tumor types with ALK or ROS1 fusions." (PMID 35233056, 2022).
tumor (continued). "Crizotinib was shown to decrease autophagic flux in ALK+ ALCL, which was important for tumor survival of NPM–ALK+ ALCL; this cytoprotective response reduced the cytotoxicity of crizotinib." (PMID 35211406, 2022). "The tumor microenvironment of ALK+ NSCLC suggested a poorly immunogenic “immune desert” of ALK+ NSCLC that also prevents the successful use of immune checkpoint inhibitors (ICI)." (PMID 35463328, 2022). "Overall, these results demonstrate that the molecular characterization of the evolution from normal T lymphocytes to in vivo NA models enabled the identification of ROR2 as a relevant cell surface marker of ALK+ ALCL tumor cells." (PMID 35246138, 2022). "In case of surgically removed NETs, the primary tumor was tested for ALK and MGMT promoter methylation." (PMID 35677534, 2022). "In advanced NSCLC, the CAP/IASLC/AMP guidelines state that ALK genetic abnormalities can be IHC screened based on highly specific antibodies (D5F3 or 5A4 clones) on CB if cytological material is the only tumor sample available." (PMID 35868633, 2022). "MET amplification was present in 15% of tumor samples from patients who were relapsing on next-generation ALK inhibitors, compared to 12% and 22% of tumor biopsies from patients who were progressing on second-generation inhibitors or lorlatinib, respectively." (PMID 36499382, 2022). "Lim CA reported that ALK IHC showed strong cytoplasmic staining of tumor cells in both LCNEC and adenocarcinoma components." (PMID 36507119, 2022). "A trend or significant differences in PD‐L1 expression between different histologic types in NSCLC, different EGFR status, and different ALK status, and different tumor tissue storage time." (PMID 34841687, 2022). "ALK fusion genes not only cause body CTL response and humoral immunity, but also induce the expression of PD-L1 on tumor cells." (PMID 36591504, 2022). "Immunohistochemistry testing also identified 49 patients (4.1%) with tumor ALK fusions among 1202 patients who underwent testing, and 16 patients (1.1%) had ROS1 rearrangements confirmed by FISH." (PMID 35877212, 2022). "In this study, conteltinib showed manageable safety profile, favorable PK properties, and anti-tumor activity in advanced ALK-positive NSCLC patients." (PMID 36424628, 2022). "In conclusion, we suggest molecular profiling of progressive tumor disease also for ALK-positive NSCLC to personalize treatment in a subgroup of ALK-positive patients." (PMID 34548910, 2021). "We previously reported that ALK-rearranged CTCs expressed a mesenchymal phenotype and high ALK protein expression in corresponding tumor tissue correlated with CK-negative areas, while tumor cells with lower CK harbored higher vimentin expression." (PMID 34272470, 2021). "The CLTC–ALK fusion gene has been confirmed to be an ALK activator in large B‐cell lymphoma and is related to tumor recurrence." (PMID 34185412, 2021). "Paradoxically, therapy is seldom decided based on the tumor molecular profile upon disease progression, and ALK‐Is are usually prescribed empirically." (PMID 34058070, 2021). "We have previously shown that tumour growth of Th‐ALK‐F1174L;Th‐MYCN‐driven NB is inhibited by treatment with lorlatinib." (PMID 33411331, 2021). "For example, SMAD4 is phosphorylated by anaplastic lymphoma kinase (ALK) at Tyr95 in ALK-positive gastrointestinal, pancreatic and lung tumors, resulting in the inhibition of tumor suppressor activity of TGF-β." (PMID 34917620, 2021). "Alectinib (AlecensaTM) is a second-generation, highly selective and potent central nervous system (CNS)-active ALK inhibitor that inhibits tumor proliferation, with specific activity against several ALK mutations." (PMID 35049690, 2021).